RNVU1-2A (RNA, variant U1 small nuclear 2A)
Synonyms: vU1.2a; RNVU1.2a; RNU1-12P; RNU1P2; U1P2A
Gene: Small nuclear RNA gene on chromosome 1 (144,551,779 to 144,551,943, reverse strand). Ensembl gene ENSG00000278099.
Gene Ontology:
Molecular function: pre-mRNA 5'-splice site binding
Biological process: mRNA 5'-splice site recognition
Cellular component: U1 snRNP
Homologues: Paralogues in human: RNVU1-7 (92% identical), RNU1-1 (92% identical), RNU1-2 (92% identical), RNU1-27P (92% identical), RNU1-28P (92% identical), RNU1-3 (92% identical), RNU1-4 (92% identical), RNVU1-18 (92% identical), RNVU1-29 (92% identical), U1 (92% identical), RNVU1-28 (91% identical), RNVU1-31 (90% identical), and 134 more.